RNU2-60P (RNA, U2 small nuclear 60, pseudogene)
Gene: Small nuclear RNA gene on chromosome 11 (111,383,092 to 111,383,219, forward strand). Ensembl gene ENSG00000253099.
Homologues: Orthologues: chimpanzee U2 (100% identical), macaque U2 (68% identical), guinea pig U2 (60% identical), mouse Gm26105 (49% identical), rabbit U2 (49% identical), tropical clawed frog U2 (41% identical), rat LOC120099523 (41% identical), tropical clawed frog U2 (39% identical). Paralogues in human: RNU2-14P (62% identical), RNU2-54P (58% identical), RNU2-58P (55% identical), RNU2-72P (55% identical), RNU2-24P (55% identical), RNU2-41P (55% identical), RNU2-22P (54% identical), RNU2-53P (51% identical), RNU2-55P (51% identical), U2 (51% identical), RNU2-10P (49% identical), RNU2-12P (48% identical), and 65 more.